IL4 (interleukin 4)
Diseases named in the same sentence as IL4 in open-access papers (continued):
Sharing a sentence is not in itself a finding about the gene and the disease.
infection (continued). "Anti-inflammatory cytokines such as IL10 and IL4 were slightly decreased around day 5-6 pi, when the infected mice succumbed to the infection." (PMID 34447981, 2021). "The spike in IL-4 production by T cells and myeloid cells in the lungs occurred at the peak of infection and just prior to the clearance of the infection in pups." (PMID 34682248, 2021). "In the rN-BmRON2 and rC-BmRON2 groups, IL-2, IL-4, IL-6 and IL-17a levels peaked on the 21st day after infection, but then decreased rapidly." (PMID 33717108, 2021). "Our results demonstrate that basophils are recruited following exposure of S. aureus on tape-stripped skin and that basophil-derived IL-4 acts at multiple checkpoints to inhibit the IL-17A response of TCRγδ+ T cells that protects against infection." (PMID 34747366, 2021). "To directly prove the role of the IL-4 signal in the A/Narita/1/2009 infection, we performed bone marrow chimera transfer (BMT) studies." (PMID 34145279, 2021). "In the advanced stage of AE infection, a reduced level of IL-4 is conducive to the growth of AE metacestodes." (PMID 34256821, 2021). "In our result, the Chinese Tibetan T. spiralis isolate induced an increase IL-4 production which reached its highest level at 11951.9 pg/mL after infection with 2,000 ML at 35 dpi." (PMID 33639942, 2021). "IL-4 is a vital immune factor that combats infection by extracellular parasites during the host immune response." (PMID 34256821, 2021). "Although not yet investigated outside bovids and cervids, the potential for IL-4 to distinguish infection states warrants further investigation." (PMID 33746980, 2021). "In our study, the mechanisms involved during early-life Ch. pneumoniae infection showed that the IL-4 expression during their early-life infection enhanced the development of AHR thereby suppressing the production of IL-4Rα2." (PMID 34226412, 2021). "But, IL-5, which is traditionally produced in response to IL-4 stimulation, is significantly reduced 48-h post infection, and remains low throughout the course of infection." (PMID 34475490, 2021). "Infection with trypanosomes results in cellular composition changes in the thymus, leading to increased production of IL-4 and IL-15 and an increased percentage of memory-phenotype cells in the thymus although these cells are CD49d+." (PMID 34398252, 2021). "Thiacloprid led to elevated expression of IL-2, IL-4, IL-10 and downregulated the expression of IgE in mice with secondary infection of AE, and ABZ exerted a consistent effect." (PMID 34488852, 2021). "On the protein level, infection with S.tm alone already caused induction of ARG1 protein, which was further increased in the presence of IL-4, but suppressed by IFNγ." (PMID 34359992, 2021). "In contrast, a slight IL-4 trigger was observed soon after the infection in the 106 group, while IL-6 and IL-10 increased around two to 10-fold." (PMID 34276650, 2021). "In humans, IL-4 has been related to patients with pre-clinical or asymptomatic infections; whereas it is rarely detected in patients with VL." (PMID 33816344, 2021). "The results showed that during the early period of infection, the expression levels of the two Th2-type cytokines IL-10 and IL-4 were higher in M. fortis than in the BALB/c mice." (PMID 34689797, 2021). "After 24 h of infection and IL-4 stimulation, we detected the highest levels of ARG1 and iNOS proteins (details not shown)." (PMID 34359992, 2021). "2-4 weeks post infection with 40 cercariae, S. mansoni antigen stimulated splenocytes show increased expression of IFNγ, as well as the Th2 cytokines IL-5 and IL-4, when compared to uninfected controls." (PMID 33953712, 2021). "Further analyses of serum cytokine levels in these animals revealed elevated levels of IL-4 in mice after two cycles of infection-treatment significantly in the 15 weeks long design or minimally in the 25 weeks long design." (PMID 34956183, 2021).
infection (continued). "Real-time quantitative PCR was used to detect the mRNA relative expression of pro-inflammatory cytokines, including TNF-α, IL-1β, IL-4, and IL-6 in the supernatant of endothelial cells 48 h after infection with influenza virus." (PMID 34414033, 2021). "Creatine uptake can reprogram macrophage M1/M2 polarization by regulating IFN-γ and IL-4 cytokine responses partly in an ATP-dependent manner under infection conditions." (PMID 34067957, 2021). "There are no statistical differences in nearly all inflammatory markers when compared to their infection-naïve CF counterparts, except in the Th2-derived IL-4 and IL-5 which demonstrate significant decreases following exposure (p = 0.046, p = 0.045)." (PMID 34475490, 2021). "Leukocytes fight infection and regulate immunity by secreting key immunomodulatory cytokines such as interleukin-1β (IL-1β), IL-6, IL-4, and tumor necrosis factor-α to promote tissue healing." (PMID 33846295, 2021). "Here the authors show that unmasking of haemagglutinin epitopes and IL-4 signals in the germinal centre contribute to broader antibody responses after infection." (PMID 34145279, 2021). "As for the late detection of enhanced serum IL-4 production in both trials, it was likely that IL-4 was generated early at the local site of infection and present later in the serum in challenged goats." (PMID 33407892, 2021). "We also measured levels of IL-4, an anti-inflammatory cytokine, in plasma before and after infection." (PMID 34929014, 2021). "Following infection with P. murina, we observed up-regulation of IL-4 production by the myeloid populations within the BALF of neonatal but not adult mice." (PMID 34682248, 2021). "Here, although Nc-Spain1H infection induced lower IFN-γ levels than Nc-Spain7, the production was more maintained over time, and higher levels of IL-4 were induced by the infection with the low-virulent isolate." (PMID 34239816, 2021). "Our findings demonstrated that the infection by T. gondii induced the IL-4, IL-10 and TGF-β1 production, however, COX-2 inhibitors decreased these cytokines and also contributed to parasitism control." (PMID 34135407, 2021). "Infection with HIV has been shown to lead to a switch from Th1 to Th2 cytokines where IL-4 and IL-10 belong." (PMID 35283948, 2021). "Decreased IFN-γ (Th1 cytokines) and increased IL-4, IL-5, and IL-10 (Th2 cytokines) during infection with S. mansoni suggested an imbalance in lymphocyte function." (PMID 34161342, 2021). "Last, the patient with mild infection who tested positive for 4 months (HL65) showed the most frequent IL-4 response in the lung, which was against S peptides." (PMID 34021148, 2021). "In the present study, following stimulation with N. caninum antigen, peripheral blood cells obtained from the infected cows were able to produce both IFN-γ and IL-4 from the end of the first week post-infection." (PMID 34239816, 2021). "In the present study, we compared the expression levels of the Th1-type cytokines IL-1β, TNF-α and IL-6 and the Th2-type cytokines IL-4 and IL-10 in susceptible host BALB/c mice and resistant host M. fortis on different days post-infection with S. japonicum." (PMID 34689797, 2021). "In contrast, IL4 displayed a degree of upregulation (p < 0.01) when in the E. canis-infected group compared with all groups throughout the post-infection phase of the experiment." (PMID 34438767, 2021). "Two of the cattle infection studies demonstrated early peaks in IL-4 expression followed by rapid decreases, while IFN-γ responses remained detectable when lesion development would be expected to begin." (PMID 33746980, 2021). "As an index of infection, fecal shedding of C. rodentium was lesser in M(IL4)-treated mice compared with untreated mice at 3, 5 and 7 days dpi (~100-fold reduction)." (PMID 34691050, 2021). "At 14 h after infection, unstimulated, IL-4- or IFNγ-treated NRAMPG169 C57BL/6N BMDM showed significantly higher nitrite levels compared to C57BL/6N BMDM." (PMID 34359992, 2021).
infection (continued). "As expected, CD4+ T cells robustly upregulated type 2 cytokines IL-4, IL-5 and IL-13 by day 7 post-infection." (PMID 34237106, 2021). "Naïve macrophages can be activated either classically into a proinflammatory M1 phenotype by IFNγ, TNF-α, and TLR ligands to defend against infection or into an anti-inflammatory M2 phenotype by IL-4 and IL-13 to aid in healing." (PMID 34539613, 2021). "For CQ treatment, levels of pro-inflammatory cytokines TNF-α, IFN-γ, IL-10 and IL-4 were also decreased significantly after infection (to 12.0, 25.0, 9.0, and 1.5 times that in controls, respectively)." (PMID 33803419, 2021). "We treated U2OS cells with different concentrations of IL-4 and performed VIAs and infections with JUNV-C1 and LCMV." (PMID 34097709, 2021). "Our data indicate that HDM-sensitized mice exhibit elevated IL-4 and IL-5 levels at various time points throughout pH1N1 infection, and conversely, lower IFN-γ on day 6 post-infection." (PMID 33653328, 2021). "IL-10 has a central role in limiting inflammation and inhibiting CD4+ T cell-mediated severe immunopathology, and IL-4 functions to enhance IFN-γ production in the late stage of infection." (PMID 33087183, 2021). "IL-4 and IL-13 share a common receptor, IL-4Rα, whose effects in CL have been widely studied in L. major infection and to some extent during L. mexicana infection." (PMID 35154068, 2021). "Nc-Spain1H infection induced higher IL4 levels in stimulated blood and a higher CD4+/CD8+ ratio in PBMC." (PMID 34239816, 2021). "During the early stage of infection, the expression of the five detected cytokines, with the exception of IL-4, was generally upregulated post-schistosome infection in M. fortis." (PMID 34689797, 2021). "In cattle, a shift towards Th2 responses highlighted by involvement of Th2 response and IL-4 and IL-6 signalling pathways occurred in the acute phase of infection." (PMID 34616397, 2021). "The assessment analysis from the infection of Ch. pneumoniae in the lungs of the 3-week-old wild-type and IL4-/- mice observed that there was a considerable load at 10 dpi and peak at 20 dpi whereas the load decreases at 30 dpi and cleared totally at 40 dpi." (PMID 34226412, 2021). "Analysis of the bronchoalveolar lavage fluid (BALF) revealed elevated levels of IL-4 on days 0, 1, 2, and 5, and IL-5 on days 0 and 5 post-infection." (PMID 33653328, 2021). "The study also observed that IL-4-/- infected mice showed drastic reduction in Chlamydia load after the infection with Ch. pneumonia." (PMID 34226412, 2021). "A study evaluated histone acetylation in individuals exposed to A. lumbricoides found that histone acetylation levels in IL-4 and IL-13 genes were altered by infection." (PMID 33692795, 2021). "Infection-induced expression of Il4 and IL-4 protein in the small intestine was similar in WT and Gpr44−/− mice." (PMID 34283207, 2021). "More importantly, the Il4−/− mice also showed a severe reduction in generation of GC B cells after A/Narita/1/2009 infection, and Il21ΔT mice showed a partial reduction of GL-7hi GC-B cells, while the Ifng−/− mice had normal GC development." (PMID 34145279, 2021). "Wild type BALB/c pups had peak levels of IL-13, IL-5 and IL-4 in the BALF at day 27 post infection with P. murina." (PMID 34682248, 2021). "In this study, whole splenocytes were stimulated for 24 h with varying concentrations of IL-4 to mimic the cytokine environment during infection/vaccination." (PMID 34006897, 2021). "Infection with O. dentatum significantly increased expression of IL4, IL13, ARG1, CCL17 and CCL26, with a concurrent trend for down-regulation of the expression of Th1-related genes such as IL8." (PMID 35069576, 2021). "The number of CD11c+CD11b+ cells (activated AMs) that were IL-4+ within the BALF was significantly increased in neonates as compared to adults at day 28 post-infection and remained elevated through clearance of P. murina." (PMID 34682248, 2021).
infection (continued). "IL-4, IL-6, IL-10, and TGF-β were associated with infection progression, while IFN-γ was correlated to tissue damage." (PMID 34276650, 2021). "The protective role of IFN-γ as well as the detrimental role of IL-4 in the outcome of experimental infection with Paracoccidioides was also demonstrated." (PMID 33668671, 2021). "In contrast, there was a significant reduction or failure in activation of type 2-related chemokines/cytokines (Cxcl12, Ccrl1, Il4, Il23a) and signature markers (Stat3, Stat5b, Stat6, Mrc1, Ahr) during infection." (PMID 34320039, 2021). "Th1 (CD3+CD4+IFN-γ+) and Th2 (CD3+CD4+IL-4+) T cells in the liver were analyzed by flow cytometry at 8 weeks post-infection." (PMID 32503644, 2020). "Alternatively, evidence suggests that low levels of IL-4 can actually promote Th1 CD8+ T cell responses to infection." (PMID 32983102, 2020). "After antigen stimulation, basophils secrete IL-4 to induce M2-type macrophages, and proteases to rapidly recruit monocytes, neutrophils, and eosinophils to the infection site." (PMID 33335529, 2020). "Specifically, mean intensity captures well the dynamics of infection, specific IgA follows tightly the laboratory data by slowly increasing to an asymptote at around 50 days post infection, while mean IL4 peaks at around 45-60 days post infection." (PMID 33226981, 2020). "Depletion of neutrophils prior to infection with L. major in BALB/c mice prevented an early burst of IL-4 mRNA expression in draining lymph nodes, suggesting a potential role for neutrophils in IL-4 production." (PMID 32948646, 2020). "To further characterize the treatment-induced immunostimulatory effects, we determined the mRNA levels of the infection-relevant cytokines IL-4 and TNF-α." (PMID 32393489, 2020). "IL4 against T. retortaeformis single infection shows a tendency to peak around 30 days post infection while an earlier peak at day 15th is observed in the dual infection." (PMID 33226981, 2020). "In this well-established experimental model, infection of BALB/c mice with L. major induces a Th2 immune response characterized by high levels of CD4+ Th2 cells producing IL-4 and low levels of CD4+ IFN-γ+ Th1 cells." (PMID 33212818, 2020). "L. major lysate-stimulated lymphocytes from EBI3−/− mice secrete fewer IFN-γ and high IL-4, IL-10, and IL-13 as compared to the lymphocytes from the control mice on the second and third week post-infection." (PMID 32849534, 2020). "Both brain mRNA levels and cytokine concentrations of IL-4 and IL-10 were shown to be upregulated after infection with A. cantonensis, whereas those of IL-2 and IFN-γdecreased." (PMID 32635653, 2020). "Th2 cells mainly secrete IL-4 and IL-10 and are mainly involved in humoral responses to extracellular infection." (PMID 33134305, 2020). "The anti-IL-4 mAb administration during the early stages of infection improves the IFN-γ-dependent host resistance in Leishmania infected WSX-1−/− mice." (PMID 32849534, 2020). "Temporal neutralization of IL-4 revealed that acute IL-4 produced within the first days of infection is critical for not only programming IL-4–producing Th2 CD4+ T cells, but for promoting IFN-γ produced by CD8+ T cells." (PMID 32948646, 2020). "In response to infection, elevated expression of IL-4 was detected in the AT, liver and SI of mice on all three diets compared to their respective uninfected groups." (PMID 33613446, 2020). "Another possible mechanism involves IL-4 production by basophils, known to potentiate B cell responses to infection in other settings." (PMID 32838342, 2020). "There were also high levels of anti-inflammatory cytokines, such as transforming growth factor type-Beta (TGFβ) from day 1 post-infection and IL-4 from day 21, which suggest active anti-inflammatory response mediated by cytokines." (PMID 33322180, 2020). "In vivo studies have determined that IL-4 is essential for the development of Th2 cells during the initial stage of infection." (PMID 32908533, 2020).
infection (continued). "In the late phase of infection, after 120 days of L. amazonensis inoculation, an upregulation of IL-4 and iNOS expression was observed in C57BL/10 when compared with C3H/He mice." (PMID 32983013, 2020). "Similar results were found in murine models infected with Plasmodium falciparum or coinfected with Toxocara canis and Toxoplasma gondii that induced an increase in TNFα, IFNγ, IL10 and IL4 brain production following infection with these parasites." (PMID 33322180, 2020). "The levels of IL-4 were significantly elevated between 3 dpi and 17 dpi and peaked at 17 dpi, 7 dpi, and 3 dpi in the low-dose, middle-dose, and high-dose infection groups, respectively." (PMID 32085808, 2020). "IL-10 expression in C57BL/10 infected mice was significantly upregulated during the experiment, while IL-4 expression was upregulated in this group only at 30 days after infection." (PMID 32983013, 2020). "We propose that the il4/13a−/−, il4/13b−/−, and il4/13a;b−/− zebrafish mutants would be valuable models to investigate the function of il4/13 paralogs in the context of infection and disease." (PMID 32641385, 2020). "IL-1α, IL-1β, IL-4, and IL-6 showed infection-specific relative responses, with higher levels in septic TKR than both aseptic TKR and primary TKA (p < 0.05)." (PMID 32708756, 2020). "In secondary infection, mice with NK cells depletion displayed significantly reduced type 1 T cell immunity, however inversely increased Tregs response as well as IL-4 production by CD4+ T cells." (PMID 32626664, 2020). "During the initial 7 days of infection, serum IL-4 reaches a peak and declines thereafter, supporting our findings that the early phase of infection is the most protective." (PMID 33117327, 2020). "Secondary infection at 10 wppt was characterized by the significant upregulation of IL-4 and IL-13 and unaltered or downregulation of type-1 cytokines, such as, IL-12p35/IL-12p40 or IFN-γ." (PMID 33276813, 2020). "After secondary infection, transcript production for iNOS, IL-6, and IL-10 was increased while Il4 was strongly reduced in sham and CLP-operated mice." (PMID 32425929, 2020). "For the intravenous infection, mice infected with strain P15 had significantly higher production in the brain of the Th2 cytokines IL-4 and IL-10, as well as the inflammatory cytokine TNF-α." (PMID 33103620, 2020). "To determine how long the effect of stress persists, we compared the gene expression of T-bet and GATA-3 or secretion of IFN-γ and IL-4 by CD4+ T cells at two- or 11-days post-infection." (PMID 32413046, 2020). "M2-type macrophages also provide protection against secondary infection of Heligmosomoides polygyrus (Hp), but M2-type macrophage differentiation during Hp infection is induced by IL-4 from CD4+ T cells in small intestine." (PMID 33335529, 2020). "Polarization toward M2 by IL-4 stimulation had no impact on virus replication in M2-/- or M2-OE macrophage populations, while IL-4 stimulation in WT macrophages elevated virus titers at 12 hr post infection (PI) however, titers declined thereafter." (PMID 33031415, 2020). "In the BALB/c model, several lines of evidence suggest that the control of infection depends not only on the induction of IFN-γ-mediated responses but also on the control of IL-10 and IL-4 cytokines that are associated with pathology." (PMID 32630347, 2020). "As infections are resolved, elevated levels of interleukin-4 (IL-4) and IL-13 promote the repolarization of macrophages to an anti-inflammatory alternative or M2 polarization state, which is accompanied by increased expression of arginase-1 (Arg1)." (PMID 32857777, 2020). "It was suggested that low levels of TNF-α, IL-2, IL-4, and IL-13 during early infection were predictive markers of chronic joint pain." (PMID 32471152, 2020). "Second, there was a significant increasing trend in the Th1/ Th2 cytokines IL-2, TNF-a, IL-4, and IL-10 on 5–7 dpi during the middle stage of infection." (PMID 33180882, 2020).